INS (insulin)
Diseases named in the same sentence as INS in open-access papers (continued):
Sharing a sentence is not in itself a finding about the gene and the disease.
sarcopenia (continued). "Furthermore, the RANK/RANKL system s instrumental in muscle metabolism, and inhibition of RANKL significantly improved muscle insulin sensitivity and reduced anti-myogenic and inflammatory gene expression in muscle, which potentially represents a novel therapeutic approach for sarcopenia." (PMID 37442968, 2023). "The present study investigated for the first time, to the best of our knowledge, the association of sarcopenia and fasting insulin level in elderly with and without T2DM, and thus extend the findings from previous research through its broader relevance to community-living elderly without T2DM." (PMID 36482911, 2022). "Thus, we observed lower INS*PA levels in the sarcopenia group." (PMID 35370985, 2022). "Therefore, the aim of the present review is to elucidate the molecular pathways involved in the crosstalk between insulin-sensitive tissues with respect to the onset and progression of sarcopenia, and how they translate into current clinical studies and future perceptive for clinical management." (PMID 34858322, 2021). "One possible reason for the effect of BCAAs on sarcopenia is that leucine, one of the BCAAs, activates the rapamycin signaling pathway, which is involved in protein synthesis in muscle, and further stimulates pancreatic beta cells to release anabolic insulin in skeletal muscle." (PMID 33579345, 2021). "However, resistance to the anabolic action of insulin has been demonstrated even in older individuals of normal muscle mass and may, therefore, precede the physical manifestations of sarcopenia." (PMID 33121164, 2020). "The insulin release deficit as well as the impaired insulin signaling leading to reduction of muscle glucose uptake present in Prdx6-/- mice, could explain by themselves, at least in part, the role of Prdx6 on sarcopenia." (PMID 32316601, 2020). "Hence, depending on the physiological context, p38 MAPK activity may lead to harmful consequences of sarcopenia and insulin resistance in the immobile muscle or beneficial effects of increased glucose sensitivity and metabolism in the contracting muscle." (PMID 32899870, 2020). "Thus, gaining control of these initial signals and processes in obese, insulin resistant, and/or aging skeletal muscle with mTOR antagonists (e.g. rapamycin, metformin), may be beneficial to limiting sarcopenia and sarcopenia-related dysfunction." (PMID 21386136, 2011). "We performed a study to determine whether sarcopenia is associated with impairment in insulin sensitivity and glucose homeostasis in obese and non-obese individuals." (PMID 22421977, 2010). "Thus sarcopenia due to age-related muscle atrophy could mean increased insulin sensitivity and more efficient glucose disposal." (PMID 22421977, 2010). "Additionally, insufficient physical activity may reduce insulin sensitivity, worsen metabolic disturbances, and accelerated the decline in muscle strength and endurance, which further contribute to the development of sarcopenia." (PMID 40860530, 2025). "Research has shown that RANKL inhibition improves muscle strength and insulin sensitivity in osteoporotic mice and humans through the RANK/RANKL/OPG signaling pathways, potentially representing a new therapeutic avenue for sarcopenia." (PMID 39852400, 2025). "However, the combination of different exercise variants, such as aerobic and anaerobic exercises, may be an adequate strategy for improving sarcopenia, since it contributes to improving insulin resistance and mitochondrial function, as well as increasing satellite cells and protein synthesis." (PMID 38921304, 2024). "Consequently, diminished insulin sensitivity not only has substantial consequences for blood glucose homeostasis, but also has a considerable effect on skeletal muscles, a situation that may prompt the onset of sarcopenia." (PMID 38643133, 2024). "Considering metabolic parameters, BMI, insulin levels and HOMA index present different behaviors according to the two classifications of sarcopenia." (PMID 38643322, 2024).
sarcopenia (continued). "Our data provide molecular and metabolic evidence supporting the use of strategies aimed to improve insulin sensitivity and to block AMPD1 to prevent sarcopenia in subjects with CKD." (PMID 36994079, 2023). "In conclusion, we suggest a role for insulin resistance, intracellular phosphate depletion, and activation of AMP deaminase in the pathogenesis of sarcopenia in CKD." (PMID 36994079, 2023). "The balance between protein synthesis and degradation is disturbed in sarcopenia, with suppression of the anabolic IGF-1/insulin-pAkt-mTOR signalling pathway and activation of the catabolic ubiquitin-proteosome system." (PMID 36678864, 2023). "Taken together, these data show that although evidence are scarce, sarcopenia are related to CAD via mechanisms that involve inflammatory mediators and insulin resistance." (PMID 36309772, 2022). "Then, MC-sarcopenia targets were filtered to obtain four core proteins, namely PIK3CA, AKT1, EGFR, and INS." (PMID 35176999, 2022). "Seven main active components (Anonaine, Eucalyptol, Neohesperidin, Obovatol, Honokiol, Magnolol, and beta-Eudesmol) and 26 target proteins of MC-sarcopenia, of which 4 were core proteins (AKT1, EGFR, INS, and PIK3CA), were identified." (PMID 35176999, 2022). "Generally, this study was conducted to evaluate the relationship between sarcopenia and high serum AST/ALT ratio and low serum INS*PA product levels among elderly Chinese participants from the WCHAT study under the background of China’s aging population." (PMID 35370985, 2022). "The fasting insulin level (AUC=0.686) and the AST/ALT ratio (AUC=0.682) were the best predictors of sarcopenia among biomarkers." (PMID 34956096, 2021). "From an economic point of view, we strongly recommend fasting insulin and AST/ALT ratio for screening for sarcopenia." (PMID 34956096, 2021). "Considering the possible efficacy of insulin, dipeptidyl peptidase 4 inhibitors (DPP4-I) are good candidates for sarcopenia treatment because they stimulate insulin secretion in a blood glucose-level dependent manner." (PMID 34063269, 2021). "Reduction in the insulin/IGF1 receptor pathway, well known to promote longevity, improves sarcopenia in worms and flies." (PMID 32857472, 2020). "In our study, we found that in the elderly with T2DM, those on metformin (regardless of whether it was metformin alone or combined with other oral hypoglycemic drugs and insulin) manifested a reduced risk for sarcopenia relative to those patients on no medication." (PMID 33083494, 2020). "Low level of adiponectin is related with decreased insulin signaling and fatty acid β-oxidation in the liver and muscles cells, encouraging an important pathophysiological mechanism in NAFLD and sarcopenia." (PMID 33204675, 2020). "Due to the increasing availability of interventions, number of VD supplements, and incidence of insulin sensitisation, geriatric researchers should combine studies on NAFLD and sarcopenia." (PMID 29387723, 2017). "These interconnected mechanisms—insulin resistance, chronic inflammation, and mitochondrial dysfunction—collectively contribute to muscle degradation in individuals with high CMI, highlighting the need for targeted interventions for sarcopenia." (PMID 40373017, 2025). "Concurrently, attenuated insulin signaling, as an anabolic hormone, hinders muscle protein synthesis (MPS) and may promote catabolism, contributing to sarcopenia, a core component of frailty." (PMID 41497955, 2025). "Leucine, a branched-chain amino acid, functions as a potent activator of mTOR signaling independent of insulin, making it particularly valuable in insulin-resistant states common in sarcopenia and cachexia." (PMID 41220691, 2025). "An older study suggested that the action of insulin does not play an important role in the development and maintenance of sarcopenia in healthy, non-obese postmenopausal women." (PMID 39459434, 2024).
sarcopenia (continued). "This abnormal response to insulin plays an important role in pathologic states such as type 2 diabetes, obesity, and MASLD, and may play a role in the development of sarcopenia." (PMID 38474786, 2024). "Fifth, we only recorded the use of oral medications and insulin treatment in participants; the correlation between specific drugs and sarcopenia was not fully explored." (PMID 37764676, 2023). "Of interest, this increase seems to be the consequence of reduced clearance of insulin as there was not a significant difference in insulin peak release following glucose exposure (40′ after glucose challenge) between sarcopenia and sham." (PMID 36994079, 2023). "Preliminary findings have suggested that insulin does not appear to have a significant effect on the development or progression of sarcopenia." (PMID 37836433, 2023). "Compared to non-sarcopenic individuals, those with sarcopenia and possible sarcopenia showed significantly lower fasting insulin (p < 0.05) in pre-frail/frail and non-frail older individuals." (PMID 36482911, 2022). "In the validation study sample of robust and pre-frail/frail elderly, sarcopenic elderly had significantly lower insulin level than the non-sarcopenia and possible sarcopenia elderly in the whole sample and the non-diabetic group (p < 0.001)." (PMID 36482911, 2022). "High AST/ALT and low INS*PA are simple biomarkers that can diagnose sarcopenia in older patients, independent of the accompanying metabolic disorders." (PMID 35370985, 2022). "In addition, good glycemic control and proper usage of medications, including insulin, GLP-1 receptor agonist, and SGLT2 inhibitor, have been reported to improve sarcopenia." (PMID 34858351, 2021). "Because reduced insulin/IGF1 signalling leads to lifespan extension in worms and hypomorphic mutants of the insulin/IGF1-like receptor daf-2 show increased healthspan including a delay in the onset of sarcopenia, we decided to use this model." (PMID 34723324, 2021). "Interestingly, the combination of amino acid supplementation regimes with vitamin D seem to benefit insulin sensitivity/T2DM and muscle mass/sarcopenia." (PMID 32213854, 2020). "On the other hand, sarcopenia promotes IR, independent of obesity, because the skeletal muscle is the primary tissue responsible for insulin‐mediated glucose disposal." (PMID 33204675, 2020). "Moreover, the accumulation of toxic lipid mediators (i.e., lipotoxicity) in skeletal muscles can induce mitochondrial dysfunctions and insulin resistance, which are both crucial determinants of CVD and sarcopenia." (PMID 31952247, 2020). "However, tilzepatide does not replace basal insulin in cases with diminished β-cell function and requires careful observation for sarcopenia." (PMID 40001315, 2025). "The differential predictive power of TyG in obese versus non-obese sarcopenic individuals likely reflects distinct pathophysiological pathways: In non-obese sarcopenia: Muscle atrophy directly impairs insulin-mediated glucose uptake, increasing the reliance on lipid metabolism." (PMID 41029714, 2025). "However, the relationship between anabolic resistance, intracellular dehydration and sarcopenia is not fully clarified for myocytes, as other key determinants are involved, including the mammalian target of rapamycin pathway, and insulin resistance." (PMID 37819614, 2024). "Our finding that a higher intake of MUFA may have positive effects on sarcopenia is consistent with previous reports indicating that MUFA may inhibit muscle atrophy by enhancing mitochondrial oxidative ability, protein synthesis, insulin sensitivity, and reducing inflammation." (PMID 37340168, 2023). "Furthermore, the results of molecular docking showed that there exists direct hydrogen bondings between the active components (Honokiol, Magnolol, and Obovatol) of MC and the core proteins of sarcopenia (AKT1, EGFR, INS, and PIK3CA), which verifies our analysis and prediction from another angle." (PMID 35176999, 2022).
sarcopenia (continued). "We hypothesized that older individuals with sarcopenia may have lower levels of fasting insulin than those without sarcopenia, considering the anabolic role of insulin in maintaining muscle mass and function." (PMID 36482911, 2022). "Indeed, 84% of patients with sarcopenia required insulin, while the percentage of patients without sarcopenia who required insulin was 68%." (PMID 34067286, 2021). "Insulin stimulates muscle protein synthesis in the young, but not older age groups, thus not providing protection against age-related muscle decline and, finally, sarcopenia." (PMID 32213854, 2020). "Although it was not possible to investigate the effects of CKD on sarcopenia, or vice versa, due to the cross-sectional nature of the study, patients with sarcopenia and CKD may share common risk factors such as insulin resistance and low vitamin D level." (PMID 26083479, 2015). "Our study results align with previous findings indicating elevated fasting blood glucose and insulin levels, along with increased HOMA-IR, in obese elderly individuals with or without sarcopenia." (PMID 38674866, 2024). "Meanwhile, we also stratified participants by age to eliminate the confounding factor, and we found that sarcopenia group had higher values of AST/ALT ratio and FSH, but lower insulin and ASMI than no sarcopenia group (P < 0.01)." (PMID 36419004, 2022). "All these explain the direct (independent of insulin effects on adipose tissue) relationship between NAFLD and sarcopenia." (PMID 33204675, 2020). "It is estimated that sarcopenia is present in about 5 to 10 % of persons over 65 years of age, whereas the T2DM patients have two to three times higher prevalence of sarcopenia than non-diabetic individuals due to glucose toxicity, insulin resistance, and oxidative stress." (PMID 30898146, 2019).
autoimmune disease (393 papers, 2006 to 2026). A disorder resulting from loss of function or tissue destruction of an organ or multiple organs, arising from humoral or cellular immune responses of the individual to their own tissue constituents. "Type 1 diabetes (T1D) is an autoimmune disease caused by the loss of self-tolerance toward insulin-producing pancreatic β-cells." (PMID 41381478, 2025). "Vitamin D plays a dual role in immune function and insulin sensitivity, and deficiency in vitamin D has been linked to a higher risk of autoimmune diseases, including T1D." (PMID 39860389, 2025). "T1D is an autoimmune disorder in which the immune system mistakenly targets beta cells, leading to insulin deficiency and lifelong dependence on external insulin administration." (PMID 40217595, 2025). "T1DM is an autoimmune disease characterized by the destruction of pancreatic β-cells, leading to an absolute deficiency of insulin." (PMID 40959421, 2025). "Elevated GlycA levels have been consistently associated with adverse lipid remodeling, reduced insulin sensitivity, and heightened risk of cardiometabolic and autoimmune diseases." (PMID 41047128, 2025). "T1D is an autoimmune disease caused by the selective immune mediated destruction of the insulin-producing beta cells, leading to a severe deficiency of insulin." (PMID 41472730, 2025). "T1DM is an autoimmune disease in which the β-cells in the islets of Langerhans in the pancreas are destroyed, leading to a loss of insulin production." (PMID 39851765, 2025). "T1DM is an autoimmune disease in which the β-cells in the islets of Langerhans are destroyed by an abnormal response of the immune system, resulting in the loss of insulin secretion." (PMID 39851765, 2025). "T1D is an organ-specific autoimmune disease caused by autoimmune-mediated destruction of insulin-producing β-cells in the pancreas, and its pathogenesis is intricate, involving a multitude of factors in its development." (PMID 38504175, 2024). "Type 1 diabetes (T1D) is an autoimmune disease that is caused by autoreactive T cell-mediated destruction of insulin-producing β cells in the pancreatic islets." (PMID 39518902, 2024). "Some patients with type 1 diabetes (T1D), an autoimmune disease that leads to absolute insulin deficiency, eventually become insulin resistant because of the continuous administration of exogenous insulin." (PMID 37779149, 2023). "These injuries originate from autoimmune diseases, which cause the immune system to target and destroy insulin-producing beta cells, hence dramatically reducing the amount of insulin produced." (PMID 36838577, 2023). "It is now concluded that the failure of the pancreatic cells to produce insulin is closely linked to a condition called autoimmune disease." (PMID 37346355, 2023). "T1D is an autoimmune disease caused by insufficient insulin secretion and the destruction of pancreatic β cells." (PMID 36998068, 2023). "T1D is an autoimmune disease that is caused by an immune system attack on insulin-producing beta cells in the pancreatic islets of Langerhans." (PMID 37720335, 2023). "T1DM often occurs in young individuals and is an autoimmune disease that arises from the selective and progressive loss of insulin-producing β cells." (PMID 37850072, 2023). "Type 1 diabetes (T1D) is an autoimmune disease that leads to the loss of insulin-producing beta cells." (PMID 37730815, 2023). "T1DM is an autoimmune disease caused by the body destroying its own insulin-producing pancreatic β cells." (PMID 36128718, 2022). "Autoimmune T1DM is a T-cell mediated autoimmune disease, resulting in the destruction of insulin-producing pancreatic beta-cells of genetically susceptible individuals, and triggered by an environmental factor." (PMID 35382047, 2022). "In experimental T1D, an autoimmune disease caused by the destruction of insulin-producing β cells by T lymphocytes, we found a preventive effect of this drug." (PMID 36528821, 2022).